LIG3 (DNA ligase 3)
Diseases named in the same sentence as LIG3 in open-access papers (continued):
Sharing a sentence is not in itself a finding about the gene and the disease.
prostate carcinoma (1 paper, 2021). A carcinoma that arises from epithelial cells of the prostate gland. "We also observed decreased risk for a SNP rs1052536 in LIG3, with a stronger association for high-grade prostate cancer." (PMID 35096612, 2021). "LIG3-rs1052536 and XRCC1-rs25489 were suggestively associated with reduced risk of high-grade prostate cancer (per minor allele: both p-trend=0.04)." (PMID 35096612, 2021). "Similar to APEX1 SNPs, several SNPs in other DNA repair genes, specifically OGG1, LIG3, and XRCC1, were associated with prostate cancer among men taking finasteride." (PMID 35096612, 2021). "Additionally, there were suggestions that LIG3-rs1052536 and XRCC1-rs25489 were associated with reduced risk of high-grade prostate cancer (both per minor allele: p-trend=0.04)." (PMID 35096612, 2021).
steatosis (1 paper, 2023). Increased lipid within the cytoplasm of cells. "When it comes to LIG3, the CC haplotype elevates the risk of steatosis, but the CA haplotype reduces it." (PMID 37511066, 2023).
toxicity (1 paper, 2019). The degree to which an agent can damage an organism. "Polymorphisms near the LIG3 gene (rs3744355, rs2074518, and rs3744357) have been reported to be associated with acute breast skin toxicity following RT both in a Japanese cohort (n = 399) and a European Caucasian cohort (n = 480)." (PMID 31196165, 2019).
tumor (20 papers, 2016 to 2025). "Tumor growth inhibition caused by RACGAP1 knockdown could be partially reversed by LIG3 overexpression, and we assessed the expression of γH2A.X, PAR and apoptotic signal in the subcutaneous tumors through IHC." (PMID 34239347, 2021). "PC-3 cells were intracardially injected into mice to construct an in vivo metastasis model, and the knockdown of Lig3 attenuated tumor load and reduced distant metastasis." (PMID 38997648, 2024). "Subcutaneous injection of PC-3 cells was used to induce tumor growth, and knockdown of Lig3 inhibited the growth of xenograft tumors and reduced tumor weight, which was reversed by overexpression of FAM84B." (PMID 38997648, 2024). "miR-22 demonstrates tumor-suppressing activity in vitro and in vivo by targeting DNA ligase III (LIG3) in MM." (PMID 37987364, 2023). "Experiments showed that compared with parental cells, the sensitivity of tumor cells to PARPi was significantly increased after LIG3 knockout; PARPi-resistant cells regained sensitivity to PARPi after LIG3 depletion." (PMID 36091750, 2022). "When cytoplasmic and nuclear expression was combined, we observed that tumours with high cytoplasmic/low nuclear LIG3 co-expression had worse PFS and worse OS compared to tumours with low cytoplasmic/low nuclear LIG3 co-expression." (PMID 34373746, 2021). "Low cytoplasmic LIG3 was seen in 221/418 (52.9%) tumours and high cytoplasmic LIG3 was observed in 197/418 (47.1%) of the tumours." (PMID 34373746, 2021). "Low nuclear LIG3 was seen in 219/418 (52.4%) of the tumours and 199/418 (47.6%) of tumours had high nuclear expression." (PMID 34373746, 2021). "We conclude that RACGAP1 exerts a tumor-promoting role via binding LIG3 to reduce apoptosis and facilitate cell growth in GBC, pointing to RACGAP1 as a potential therapeutic target for GBC." (PMID 34239347, 2021). "Inducible LIG3 downregulation resulted in a significant reduction of cell viability and clonogenicity in vitro and inhibition of tumor growth in vivo." (PMID 30120376, 2019). "We here provide evidence that miR-22 acts as tumor suppressor in MM cells in vitro and in vivo, via LIG3 targeting." (PMID 30120376, 2019). "Taken together, our findings provide proof of concept that RHM targets LIG3 addiction in MM and may represent therefore a novel promising anti-tumor natural agent to be investigated in an early clinical setting." (PMID 36273153, 2022). "A total of 418 tumours were suitable for analysis of LIG3 expression." (PMID 34373746, 2021). "In addition, when cytoplasmic and nuclear expression was combined, only tumours with high cytoplasmic/low nuclear LIG3 co-expression had worse PFS and OS compared to tumours with low cytoplasmic/low nuclear LIG3 co-expression." (PMID 34373746, 2021). "To conclude, our study shows, for the first time, the tumor-promoting role of RACGAP1 in GBC which is partially mediated by binding to and stabilizing LIG3." (PMID 34239347, 2021). "Gaining insight into the mechanistic role of Lig3 and alt-NHEJ in NBL tumor initiation and in tumorigenesis will be an important step towards implicating this pathway in NBL pathogenesis." (PMID 29238067, 2017). "Targeting the MMEJ pathway (e.g., via LIG3 inhibitors and POLQ inhibitors) could disrupt eccDNA biogenesis, potentially sensitising tumours to chemotherapy." (PMID 40984821, 2025). "Alternative end-joining factors were expressed at moderate levels in the normal cerebellum and in the GNPs and at significantly higher levels in the tumor cells, except Lig3, detected neither in the healthy cerebellum nor in the tumors in these animals." (PMID 30420702, 2018). "Furthermore, Lig3, Lig1 and PARP1 silencing also significantly blocked protein expression of neuronal developmental and NBL tumor markers (TH, Phox2b, TRKB) in differentiating NCSC-MYCN cells, quantified by Western blot analysis." (PMID 29238067, 2017).
tumor (continued). "An important question is whether Lig3, Lig1, or PARP1 inhibition could block tumor development, an area of our ongoing studies." (PMID 29238067, 2017). "Moreover, the negative effect of LIG3 rs4796030 A>C polymorphism significantly associated with the patients in the groups of BMI ≥ 24, clinical stages III/IV and tumor at the left." (PMID 33391423, 2021). "Collectively, these results provide new evidence that these three factors (Lig3, Lig1, and PARP1) have a functional role in MYCN oncogenic activity in human NCSC, and sets precedence to investigate alt-NHEJ and non-canonical DNA repair factors in NBL tumor initiation and progression." (PMID 29238067, 2017).
cancer (19 papers, 2012 to 2025). A tumor composed of atypical neoplastic, often pleomorphic cells that invade other tissues. "In conclusion, our study highlights elevated levels of AAbs against IFNA and other antigens implicated in various cancers, as well as associations between AAbs targeting LIG3 and BIRC6 with more favorable treatment outcomes." (PMID 40768895, 2025). "The identification of 132 somatic missense variants further underscores the relevance of LIG3 in cancer biology, as somatic mutations are often drivers of oncogenesis." (PMID 40493574, 2025). "This cancer-type-specific association highlights the complex role of LIG3 in different malignancies." (PMID 40493574, 2025). "A growing body of research indicates that LIG3 SNPs are significantly associated with cancer susceptibility and recurrence 5-7, 11-14." (PMID 31737108, 2019). "Similar to BRIP variants, knowledge is very limited about the influence of LIG3 (DNA ligase 3) gene polymorphisms to GC cancer susceptibility." (PMID 28415781, 2017). "The expression levels of LIG3 gene are associated with prognosis in several cancers, suggesting that both SNPs and expression may function as markers for clinical results." (PMID 40493574, 2025). "LIG3’s expression can increase genome instability and cancer risk, which could lead to greater chance of poor outcomes for Black patients compared with White." (PMID 33920951, 2021). "In addition to its role on nuclear DNA repair, LIG3 gene encodes also the principal DNA ligase involved in mtDNA replication and repair, essential requisite to sustain mitochondrial contribute to cancer cell survival." (PMID 30120376, 2019). "Homozygous mutation of LIG3 confers a high risk for pancreatic and other forms of cancer." (PMID 22905093, 2012). "Our findings highlighted the cancer-type-specific relevance of LIG3 expression in survival outcomes, warranting further investigation into its functional mechanisms." (PMID 40493574, 2025). "The high PPI enrichment value (1.11e-16) suggests that LIG3 is a central player in these pathways, further emphasizing its importance in cancer biology." (PMID 40493574, 2025). "This is consistent with compensatory action of Lig3 in replication context in case of Lig145 and with one of the previous reports on the role of Parp1 obtained in a human cancer cell line HEK29346,47." (PMID 35701408, 2022). "miR-22 can also inhibit the LIG3 gene and affect cancer cell mitochondrial structure and function." (PMID 36077994, 2022). "Since LIG3 has been demonstrated as a crucial anti-solid and -hematologic tumor target, additional works are required to be performed to investigate the connection between LIG3 acetylation and repair efficiency in cancer." (PMID 33194676, 2020). "A number of studies have shown that polymorphisms in the DNA ligase III (LIG3) gene, one of the key genes in the error-prone alternative NHEJ (a-NHEJ) pathway for DNA double-strand break (DSB) repair, are associated with a variety of cancers." (PMID 31737108, 2019). "The remaining shared hits in the 5 cancer cell lines included X-Ray Repair Cross Complementing 1 (XRCC1), PARP1, Replication Protein A1 (RPA1) and DNA ligase 3 (LIG3)." (PMID 36386669, 2022). "It has been reported that LIGs (including LIG1, LIG3 and LIG4) play important roles in the occurrence and progression of many cancers." (PMID 34825062, 2021). "Therefore, cancer cell cycle arrest and apoptosis that occur in the presence of RACGAP1 knockdown is partly due to failure of DNA damage repair induced by LIG3 suppression." (PMID 34239347, 2021).
infection (3 papers, 2011 to 2018). The state of being infected such as from the introduction of a foreign agent such as serum, vaccine, antigenic substance or organism. "Early during infection, viral genomes also associate with factors that have known roles in the recognition or processing of DNA breaks, including RPA1, PARP1, PARP14, and ligase 3 (LIG3)." (PMID 30018111, 2018). "Upon infection, the levels of HBV cccDNA and core protein were markedly lower in HepG2-NTCP cells with LIG1 or LIG3 knock-down compared to the control knock-down cells, suggesting that LIG1 and LIG3 are also required for the first round HBV cccDNA formation during de novo infection." (PMID 29287110, 2017).
metabolic disease (1 paper, 2021). A congenital disorder (due to inherited enzyme abnormality) or acquired (due to failure of a metabolically important organ) disorder resulting from an abnormal metabolic process. "The disorders known to be associated with the affected genes range from embryonic lethality (e.g., MRPL55 and LIG3) and metabolic diseases (e.g. acyl-CoA synthetase long chain family member 5 (ACSL5)) to neurodevelopmental disorders (e.g., methionyl-tRNA synthetase 2 (MARS2))." (PMID 34915862, 2021).
LIG3 also shares sentences with these, for which no sentence is quoted: hepatocellular carcinoma (2 papers); anencephaly (1); ataxia telangiectasia (1); autoimmune disease (1); Autoimmunity (1); B-cell lymphomas (1); bladder cancer (1); brain diseases (1); breast (1); emphysema (1); esophageal squamous cell carcinoma (1); liver cancer (1); lymphoma (1); melanoma (1); mesothelioma (1); mitochondrial disease (1); mitochondrial neurogastrointestinal encephalomyopathy (1); myeloid leukemia (1); myopathy (1); neurodevelopmental disorder (1); neuropathy (1); non-melanoma skin carcinoma (1); non-small cell lung carcinoma (1); oropharyngeal squamous cell carcinoma (1); pancreatic cancer (1).